ATG5 (autophagy related 5)
Diseases named in the same sentence as ATG5 in open-access papers (continued):
Sharing a sentence is not in itself a finding about the gene and the disease.
tumor (continued). "We found that knocking down of ATG5, an essential autophagy gene, reverses the antitumour effect of TRB3 depletion in tumour cells as demonstrated by the 5-Ethynyl-2′-deoxyuridine (Edu) proliferation assay and the transwell invasion assay." (PMID 26268733, 2015). "We treated the tumor cells with TMZ-Se in the absence or presence of the autophagy inhibitors, 3-MA, bafilomycinA1 or Atg5 siRNA, and then measured cell viability." (PMID 22496897, 2012). "This suggests that while ATG5, as one of the core components of the autophagy-initiating machinery, may be required for BECN1-mediated tumor-suppressive effects of DHX9 silencing, only BECN1 functions as the essential triggering factor." (PMID 40659605, 2025). "The activation of autophagy-related genes, such as ATG5 and ATG7, facilitates the shift from tumor suppression to cytoprotective autophagy and hence, alteration in expression of these gene may improve the effectiveness of chemotherapeutic agents." (PMID 40176914, 2025). "However, the antitumor effect was markedly greater in mice treated with ATG5-knockout CAR-T cells, where the average reduction in tumor area over the first 17 days post-treatment was 3.693 mm2 per day." (PMID 41279553, 2025). "Additionally, administration of the autophagy inhibitor 3-methyladenine (3-MA) led to increased MTOR expression and downregulation of ATG5, ATG7, and BECN1, resulting in reduced tumor volume and elevated apoptosis cell death." (PMID 41502518, 2025). "In vivo experiments showed that the tumor volume of the shRNA group was significantly smaller than that of the SC-shRNA group (P<0.01), the expression of CD46 and TREM1 was decreased considerably, and the expression of LC3B and ATG5 was higher (P<0.01)." (PMID 40475017, 2025). "In conclusion, our previous and current findings provide the compelling evidence that Atg5 functions either as a tumor suppressor in the cell with normal autophagy function or becomes a tumor inducer under autophagy‐deficient conditions during tumorigenesis." (PMID 38826147, 2024). "We established stable MEF clones overexpressing the Atg5 transgene in the background of Atg7 gene knockout (Atg7−/‐MEF), which showed increased cell proliferation, migration, and colony formation in vitro, and transient induction of tumor formation in vivo." (PMID 38826147, 2024). "Studies have demonstrated that ATG5 and ATG7 regulate ferroptosis-mediated tumor IT." (PMID 39281375, 2024). "Without functional autophagy, Atg5 becomes a weak oncogenic factor that promotes initial tumor formation, but needs other oncogenic factors to prolong further tumor development." (PMID 38826147, 2024). "Moreover, we determined the expression of NCX1, CD138, Ki67, ATG5 and ATG7 in tumor sections by immunohistochemical staining." (PMID 38711131, 2024). "Finally, KO of autophagy-related genes enhanced cell death in the presence of IFN-γ (ATG2A, ATG5, ATF3, and ATF16L1), consistent with autophagy mediating cancer cell resistance to anti-tumor T cells." (PMID 36669486, 2023). "However, using autophagy inhibitors such as 3‐MA and HCQ to inhibit autophagy‐related genes like ATG5, ATG7 and Beclin 1 can re‐sensitize TAM‐resistant tumor cells." (PMID 37837401, 2023). "Autophagy-related genes play an important role in tumor progression, and some studies have shown that hypoxia-induced acetylation of PAK1 can enhance autophagy and promote the occurrence of GBM through phosphorylation of ATG5." (PMID 37460467, 2023). "Mechanistically, SH3BGRL binds with ATG5 and stabilizes it to drive the basal liver cell autophagy through inhibition of Src and its downstream ERK and AKT signaling pathways that generally lead to tumor cell survival and proliferation." (PMID 37138798, 2023). "Here, we first unveil that SH3BGRL binds with ATG5 and stabilize it to trigger autophagy initiation, indicating the crucial physiological function of SH3BGRL in cell homeostasis, while linking the autophagy and tumor progression together." (PMID 37138798, 2023).
tumor (continued). "Therefore, we evaluated the expression of the main autophagy markers ATG5, Beclin 1 and LC3 in tumor tissue." (PMID 35751683, 2022). "In addition, compared to the H446 tumor, H446/EP had a similar ratio of LC3II/LC3I, but a significantly lower level of ATG5 and p62." (PMID 35292022, 2022). "Thus, we analyzed the correlation of tumor weight, LC3II/LC3I, ATG5, p62, and miR-199a-5p in all the samples we collected." (PMID 35292022, 2022). "ATG5, a gene essential for autophagy, and AIM1, a gene implicated in melanoma, showing generally low expression in ENKTL, appear to play a tumor-suppressor role, although the exact function in ENKTL is not clear." (PMID 35054466, 2022). "The deletion of ATG5 or ULK1 induced a decreased expression of genes involved in the cell cycle and/or replication, supporting the suggestion that autophagy is required for tumor cell expansion." (PMID 35884522, 2022). "A mouse model with carcinogenic KRAS expression in pancreatic cells in the presence of two, one, or no Atg5 gene copies found that reduced Atg5 protein levels enhance tumor formation, but the absence of Atg5 prevents tumorigenesis." (PMID 35740481, 2022). "Western blot was performed to detect the protein levels of ATG5 and LC3-II in tumor tissues." (PMID 34790665, 2021). "Also, as compared to ATG5 and ATG7, Beclin1-dependent and Beclin1-independent properties play an important role during embryonic development and tumor suppression." (PMID 33628386, 2021). "TLR9 overexpression increased HCC cell proliferation, whereas TLR9 inhibition from hydroxychloroquine (HCQ) decreased HCC cell proliferation, tumor growth, oxidative stress marker (SOD1), and the formation of autophagosome bodies (reduced ATG5 and Beclin-1 expression)." (PMID 34203465, 2021). "Meanwhile, autophagy suppression due to ATG5 knockdown increases tumor cell death in non-malignant cells such as fibroblasts." (PMID 34947979, 2021). "Using Univariate Cox regression analysis, the results confirmed negative correlations between overall survival and gender (p = 0.014), tumor invasion (p = 0.000), lymph-node metastasis (p = 0.000), TNM stage (p = 0.000), and high CDKL3 (p = 0.014) and ATG5 expression (p = 0.007) in ESCC patients." (PMID 32974198, 2020). "Additionally, the excised tumor masses showed that GAS8-AS1 overexpression triggered an increase in GAS8-AS1, ATG5, and ATG7 and a reduction in miR-187-3p and miR-1343-3p." (PMID 33230459, 2020). "Moreover, when autophagy is blocked by knockout of ATG5 or ATG7 in these cells, tumor growth in vivo is delayed." (PMID 31968668, 2020). "Comparatively, deletion of downstream autophagy genes Atg5 or Atg7 permitted development of benign tumors that failed to progress to malignant cancers." (PMID 33381037, 2020). "In LysMcreAtg5fl/fl mice, in which myeloid cells lacked Atg5 expression, there were less Treg TILs, tumor cell proliferation rate reduction, and a significant increase in both MHC-II expression and IFN-γ production." (PMID 33335860, 2020). "Hence, the observed growth phenotypes most probably result from early effects of ATG5 and RAB21 depletion on tumor growth and would presumably be stronger in the context of a prolonged knockdown (or knockout)." (PMID 31383875, 2019). "Additionally, ATG5 and BECLIN-1 levels are downregulated in hepatic tumor, compared to adjacent non-tumor regions." (PMID 30849993, 2019). "Surprisingly, knockdown of ATG5 and RAB21 in SW480 and LoVo resulted in increased tumor growth, whereas SW620 and HT29 cell lines were non-responsive to autophagy inhibition and grew to similar extents whether in control or treated conditions." (PMID 31383875, 2019). "Since either upregulation of ATG16L2 expression or downregulation of ATG16L1 expression in human tumors should increase the competitive binding of ATG16L2 to ATG5, we calculated the ATG16L2:ATG16L1 mRNA expression ratio in normal and tumor samples from the TCGA mRNA datasets." (PMID 31636955, 2019).
tumor (continued). "In KRAS-mediated lung tumors, the depletion of Atg5 or Atg7, two mitophagic effectors involved in LC3/GABARAP lipidation, has induced a reduction in tumor burden and an increase in survival compared to the counterpart even if malignancies present a faster tumor-initiation stage." (PMID 31210843, 2019). "With TMAs containing punches of 10 non-neoplastic testicular tissues retrieved from contralateral testicular biopsies of patients with TGCT and punches from 191 TGCT tumor patients, we employed immunohistochemical methods to stain for key autophagy regulators, ATG1, ATG5, and ATG16L1." (PMID 30245976, 2018). "Additionally, immunostaining analysis showed that ATG5 and ATG16L1 expression levels were significantly decreased in the HepG2/miR-142-3p xenografts compared with the HepG2/control tumour xenografts after sorafenib treatment." (PMID 29472524, 2018). "Immunohistochemical staining employing tumor tissues showed that AQTGTGKT peptide decreased expression levels of ATG5 and pAMPKαThr172, but not CAGE." (PMID 30619741, 2018). "Unexpectedly, the expression level of ATG5 in both normal and tumor tissue did not exhibit significant correlation with the genotypes of ATG5:rs1322178, ATG5:rs3804329, or ATG5:rs671116." (PMID 29207660, 2017). "The low rate of tumor development and growth precluded further in vivo analysis of the effect of CR in Atg5−/− tumors, although previous studies have established that LC3 puncta formation is negligible in Atg5−/− tumors." (PMID 27651895, 2016). "ATG5-defective H460 (ATG5KD) tumours were sensitized to irradiation and detected a significant enhancement in irradiation-induced tumour growth delay compared with autophagy-competent control tumours." (PMID 24037090, 2014). "Furthermore, the tumor tissues of LC3 and Atg5 expression were increased in the combined treatment compared with ATO or IR treatment alone." (PMID 22363680, 2012). "However, we observed durable tumor control and long-term remission after a single infusion of ATG5-knockout CAR-T cells, which suggests that the absence of memory markers does not preclude sustained therapeutic benefit." (PMID 41279553, 2025). "For example, gene inhibition of Atg5 or Atg7 has demonstrated that the absence of autophagy in tumor‐prone mouse models increases the incidence of precancerous lesions and tumors after activation of the RAS pathway, indicating that autophagy can prevent cancer development." (PMID 39648951, 2025). "Atg5 may act as the first “hit” to induce a benign tumor formation, however, the second “hit” to prolong tumor development and progression was not activated under autophagy‐deficient conditions." (PMID 38826147, 2024). "Although PtdSer is also present on the surface of apoptotic tumor cells and other efferocytosis receptors exist on DCs, such as the CD36-PtdSer pathway that mediates the recognition and uptake of apoptotic tumor cells, it is normally inhibited by the presence of the autophagy protein ATG5." (PMID 38835772, 2024). "Although MIEAP or ATG5 KO did not alter the cell proliferation rate or differentiation status in mice and their expression levels are not related to prognosis in human PTCs, our results suggest that these molecules are tumor suppressors." (PMID 36187114, 2022). "For instance, human protein farnesyltransferase inhibitors (FTIs), which have been successful at suppressing tumour growth in pre-clinical studies, have been shown to induce dormancy in MCF-7 cells by upregulating protein expression levels of autophagy markers such as the Atg12 and Atg5 conjugate." (PMID 35563661, 2022).
tumor (continued). "Moreover, we found that cell transfection with an hsa-miR-30a-3p mimic blocks protective autophagy through ATG5, ATG12, and Beclin 1 suppression, which in turn increases cancer cell sensitivity to chemotherapeutic interventions in vitro and reduces tumor growth and muscle invasion in vivo." (PMID 35449123, 2022). "In addition, autophagy-related gene are reported as tumor suppressor including BECN1 and Atg5." (PMID 33802602, 2021). "Moreover, this study shows that activation of the ATG5-mediated autophagy in response to a lack of glutamine is a tumor survival strategy to withstand radiation-mediated cell damage." (PMID 34335968, 2021). "Moreover, tumor cells engineered to lack Atg5 or to express constitutively active AKT failed to respond to the ISO/OXA combination treatment in the immunocompetent setting." (PMID 33243998, 2020). "Genetic inhibition of autophagy using ATG5 siRNA promotes the ENZ-mediated apoptosis, and the combination treatment with ENZ and CQ improves the therapeutic efficacy by restoring the sensitivity against ENZ via the reduction of tumor growth and induction of apoptosis." (PMID 33375363, 2020). "Moreover, tumor cells engineered to lack Atg5 or to express the ATP-destroying ectoenzyme CD39 failed to respond to chemotherapy alone or in combination with aspirin even in the context of an intact immune system." (PMID 33298861, 2020). "In this study, knockdown of ATG5 in primary AML cells resulted in impaired engraftment of human cells in immunodeficient NSG mice, an observation that is in contrast to previous work and would rather suggest a tumor-promoting role for autophagy in this context." (PMID 30678185, 2019). "Of note, although knockdown efficiencies were variable between cell lines and did not persist over the full time course of tumor growth, increased p62 staining was observed in ATG5- and RAB21-depleted CRC tumors, suggesting that autophagy was impaired, in our CAM model." (PMID 31383875, 2019). "Moreover, that overexpression of TSSC3 enhanced autophagy and knockdown of ATG5 blocked TSSC3-induced autophagy were further confirmed in vivo using TEM and IHC staining of TSSC3 and autophagy related proteins of human xenograft tumor tissues." (PMID 30092789, 2018). "However, neither OS nor PFS differed significantly in patients with different expression levels of ATG5 in tumor tissue (data not shown)." (PMID 29207660, 2017). "In agreement with our preliminary data using 3-methyl adenine, and our ER stress data showing increased Beclin1 expression, knock down of Beclin1 or of ATG5 suppressed, but did not completely abolish, tumor cell killing by the (ruxolitinib + lapatinib) drug combination." (PMID 27379204, 2016). "Notably, Atg5 mosaic knockouts develop tumors only in the liver, but not in other tissues, suggesting that hepatocytes have a dependence on the tumor-suppressive role of autophagy." (PMID 26561802, 2015). "Similarly, growth inhibition induced by gefitinib or erlotinib in A549 cells was enhanced after autophagy was inhibited by the knockdown of ATG5 or ATG7, two essential components for the formation of autophagosome, confirming that autophagy protected tumor cells from EGFR-TKIs induced cell death." (PMID 21655094, 2011). "Additionally, tumor cells lacking the ATG5 gene, a protein involved in the early stage of autophagosome formation, show an increased response to ER stress, suggesting that the inhibition of autophagy can intensify ER stress in tumor cells and induce apoptosis." (PMID 40723802, 2025). "Notably, the xenograft mouse model showed that clone A of Atg5‐overexpressed Atg7−/− MEF cells induced temporal tumor formation, but could not prolong further tumor growth." (PMID 38826147, 2024).
tumor (continued). "Thus, we revealed that circTGFBR2 is a novel tumor promoter circRNA in hepatocytic exosomes and promotes HCC progression by enhancing ATG5–mediated protective autophagy via the circTGFBR2/miR-205-5p/ATG5 axis, which may be a potential therapeutic target for HCC." (PMID 37474520, 2023). "Moreover, genetic ablation of ATG5 in a KRAS-driven mouse model of PDAC enhances the metastatic potential of tumor stem cells, implying an anti-metastatic effect of autophagy under certain circumstances, especially during the initial stages of tumor development." (PMID 36505808, 2022). "In addition, silence of the Atg5 or Atg7 also did not sensitize tumor cells to other PI3Kis." (PMID 34844627, 2021). "However, the inhibition of ATG5, ATG7, and Beclin 1 augmented the migration and invasion in glioblastoma cells, indicating that autophagy inhibition may serve as potential anti-tumor therapy approach." (PMID 32426106, 2020). "Interestingly, the CQ-induced normalizing effects on the tumor vasculature could not be phenocopied in vivo and in vitro by deleting Atg5 in ECs." (PMID 30949450, 2019). "Thus, in the context of an absent cellular immune response, ATG5-deficient (ATG5KD) tumours were significantly more sensitive to IR than autophagy-competent control tumours, as revealed by the comparison of tumour volumes measured before and after 10 days of irradiation." (PMID 24037090, 2014). "Moreover, another study showed that CD4+ T cells lacking Atg3 or Atg5 can increase IL-9 expression and autophagy inhibition enhanced T helper 9 cell anticancer effects in vivo, and mice with T cell-specific deletion of Atg5 showed decreased tumor outgrowth in an IL-9-dependent manner." (PMID 38627815, 2024). "We found that attenuation, even not complete depletion, of ATG5 abundance alone is sufficient to increase IFN-γ expression by IFN-γ producing cells at both early and later tumor stages in Atg5flox/flox mice." (PMID 35966597, 2022). "There was no noticeable difference in tumor expansion between KRASG12V;Atg5+/+ and KRASG12V;Atg5∆/∆ tumor cells in host with the same genotype (lane 1 vs lane 2, lane 3 vs lane 4)." (PMID 35966597, 2022). "Third, a high ATG5 protein level was positively correlated with the overall survival and DFS in patients with large tumor size (T3 and T4) or patients without lymph node invasion and radiotherapy." (PMID 33926066, 2021). "Since LAP involves autophagy genes such as ATG5, ATG7 and BECN1 but not FIP200, it represents a distinct non-autophagy function of these other autophagy genes that can impinge on anti-tumor immunity." (PMID 32743346, 2020). "No significant changes were observed in PARP or Caspase 3 cleavage between control and ATG5- or RAB21- depleted cells, indicating that apoptosis induction was not responsible for the decreased tumor size in HCT116 cells." (PMID 31383875, 2019). "There were no major macroscopic differences between control and ATG5- or RAB21-depleted tumors for all cell types, suggesting that the varying tumor sizes could be due to the modulation of apoptosis or proliferation." (PMID 31383875, 2019). "Furthermore, HULC overexpression in vivo induced tumor formation, and reduced ATG7, LC3 expression, while inducing SQSTM1 expression; however, we found that HULC overexpression did not influence ATG5, ATG12, Beclin-1, VPS34, P150 or UVRAG expression." (PMID 29022892, 2017).
tumor (continued). "The data showed that both ATG-5 and MRP-1 were positively expressed in cancer and non-cancerous tissues, which suggest that ATG-5 and MRP-1 may be induced by chemotherapy in both tumor and non-tumor tissues." (PMID 25329677, 2014).